LINC01355 (long independently transcribed non-coding RNA 1355)
Synonyms: HYPAL
Gene: Long non-coding RNA gene on chromosome 1 (23,281,307 to 23,287,488, reverse strand). Ensembl gene ENSG00000261326.
Diseases named in the same sentence as LINC01355 in open-access papers:
LINC01355 is named in the same sentence as 6 diseases in open-access papers, as found by Europe PMC text mining. Sharing a sentence is not in itself a finding about the gene and the disease. The quoted sentences say what the papers report.
breast carcinoma (4 papers, 2019 to 2024). "LINC01355 interacts with FOXO3a protein and prolongs the half-life of FOXO3a protein, leading to transcriptional repression of Cyclin D1 to induce breast cancer cell cycle arrest." (PMID 38505423, 2024). "LINC01355 was reported to be a tumor suppressor in breast cancer and a tumor enhancer in gastric cancer and oral squamous cell carcinoma." (PMID 36213821, 2022). "Overexpression of LINC01355 significantly inhibited proliferation, colony formation, and tumorigenesis of breast cancer cells." (PMID 31243265, 2019). "As breast cancer cell lines showed a general downregulation of LINC01355, we performed LINC01355 gain-of-function studies in both MCF7 and MDA-MB-231 cells." (PMID 31243265, 2019). "We found that overexpression of LINC01355 significantly inhibited the proliferation and colony formation of breast cancer cells." (PMID 31243265, 2019). "Clinically, LINC01355 downregulation is significantly associated with tumor size and TNM stage in breast cancer." (PMID 31243265, 2019). "We demonstrate that LINC01355 expression is underexpressed in breast cancer tissues and cell lines compared with their normal equivalents." (PMID 31243265, 2019). "LINC01355 acts as a tumor suppressor in breast cancer, which is ascribed to enhancement of FOXO3-mediated transcriptional repression of CCND1." (PMID 31243265, 2019). "Biochemically, LINC01355 overexpression inhibits the expression of cyclin D1 in breast cancer cells." (PMID 31243265, 2019). "Functionally, LINC01355 knockdown renders a proliferation advantage to breast cancer cells, whereas ectopic expression of LINC01355 suppresses the proliferation and colony formation of breast cancer cells." (PMID 31243265, 2019). "Re-expression of LINC01355 suppresses the growth and tumorigenesis of breast cancer cells, which involves the stabilization of FOXO3 and enhancement of FOXO3-mediated transrepression of CCND1." (PMID 31243265, 2019). "Downregulation of LINC01355 was significantly correlated with larger tumor size (P = 0.0171) and advanced clinical stage (P = 0.0079) of breast cancer." (PMID 31243265, 2019). "LINC01355-mediated inhibition of breast cancer cell proliferation and clonogenicity were reversed by knockdown of FOXO3." (PMID 31243265, 2019). "We found that LINC01355 was significantly downregulated in breast cancer tissues relative to normal breast tissues (P = 0.0059)." (PMID 31243265, 2019). "Taken together, we provide first evidence that LINC01355 acts as a tumor suppressor in breast cancer." (PMID 31243265, 2019). "In vivo data further validate the suppressive activity of LINC01355 in breast cancer tumorigenesis." (PMID 31243265, 2019). "Importantly, LINC01355-mediated suppression of breast cancer growth was reversed by knockdown of FOXO3 or overexpression of CCND1." (PMID 31243265, 2019). "Re-expression of LINC01355 may provide a potential therapeutic strategy to block breast cancer growth and progression." (PMID 31243265, 2019). "Downregulation of LINC01355 contributes to aggressive phenotype of breast cancer." (PMID 31243265, 2019). "Taken together, LINC01355 acts as a tumor suppressor in breast cancer." (PMID 31243265, 2019). "In addition, it remains to be determined whether LINC01355 can exert its tumor-suppressing activity in other cancers besides breast cancer." (PMID 31243265, 2019). "Consistent with the finding that knockdown of FOXO3 abrogates LINC01355-induced downregulation of CCND1, FOXO3 depletion reverses the inhibitory effect of LINC01355 on breast cancer cell proliferation and tumorigenesis." (PMID 31243265, 2019).
renal carcinoma (1 paper, 2022). A carcinoma arising from the epithelium of the renal parenchyma or the renal pelvis. "The results showed that the expressions of RNF139-AS1, SRD5A3-AS1, LINC01094, USP30-AS1, LACTB2-AS1, and LINC01355 were elevated in renal carcinoma cells, and the expressions of RAP2C-AS1 and LINC00551 were reduced in renal carcinoma cells compared with normal renal proximal convoluted tubule cells." (PMID 35664432, 2022).
tumor (4 papers, 2019 to 2023). "In vivo studies confirmed that FOXO3 deficiency abolished the suppression of MCF7 xenograft tumor growth induced by LINC01355." (PMID 31243265, 2019). "For example, previous studies have demonstrated the important role of LINC01355 as a tumor suppressor or activator gene." (PMID 37265963, 2023). "In addition, LINC01355 was found to activate the Notch pathway to help tumor cells evade T cell tumor immunity." (PMID 34355042, 2021). "Decrease of LINC01355 inhibited tumor growth and triggered T cell infiltration in xenograft." (PMID 34355042, 2021). "Therefore, we propose that the FOXO3/CCND1 axis plays an essential role in LINC01355-mediated tumor suppression." (PMID 31243265, 2019).
cancer (3 papers, 2018 to 2021). A tumor composed of atypical neoplastic, often pleomorphic cells that invade other tissues. "LINC01355 has been demonstrated to be dysregulated in several cancers." (PMID 34355042, 2021). "LINC01614, CTD-2547G23.4, LINC01355, MALAT1, CTD-2349P21.9 and RP11-468E2.10 were over-expressed, whereas RP11-672A2.4 was under-expressed in cancers." (PMID 29303984, 2018).
LINC01355 also shares sentences with these, for which no sentence is quoted: gastric cancer (3 papers); oral squamous cell carcinoma (1).